VIM (vimentin)
Diseases named in the same sentence as VIM in open-access papers (continued):
Sharing a sentence is not in itself a finding about the gene and the disease.
metastatic tumors (60 papers, 2008 to 2025). "In summary, Kdm8 restrains phenotypic reprogramming by limiting the loss of differentiation and expression of the EMT marker Vimentin, thereby potently suppressing metastatic disease." (PMID 40909661, 2025). "Clinical evidence supports a causal link between vimentin expression and the metastatic process, whereby vimentin is highly expressed in primary and metastatic tumors." (PMID 38534324, 2024). "Third, IHC of E-cadherin and vimentin in liver metastatic tumor, lung metastatic tumor and soft tissue metastatic tumor models revealed that loss of DDX21 enhanced E-cadherin but reduced vimentin expression." (PMID 37029300, 2023). "The expression of vimentin, an intermediate filament protein, is associated with higher metastatic disease, and poor prognosis and survival of patients with multiple tumor types, including NSCLC patients." (PMID 37620594, 2023). "Higher level of TAP1 in metastatic tumors were associated with higher levels of vimentin and LEF1, while associated with lower level of E-cadherin." (PMID 34957213, 2021). "Additionally, IHC was adopted to evaluate the expression of EMT‐associated genes, including E‐cadherin and vimentin, in primary tumor and lymph node metastatic tumor." (PMID 31433128, 2019). "Epithelial-mesenchymal transition (EMT) is a hallmark of metastatic neoplasms, including BrC, and is involved in the concurrent downregulation of epithelial markers such as E-cadherin and α-catenin, and upregulation of mesenchymal markers such as vimentin, β-catenin, and Snail." (PMID 26360780, 2015). "Still, the IHC stain findings in this case align with the typical meningioma staining patterns: strong vimentin positivity in both the primary and metastatic tumors, confirming meningioma metastasis to the lungs." (PMID 41560863, 2025). "Of note, primary and metastatic tumors of MT‐PHHs‐sgRELA upregulated N‐cadherin and vimentin expression, but downregulated E‐cadherin expression, compared to lumps of MT‐PHHs‐sgCtrl dissected from the control group." (PMID 40919676, 2025). "Lower Panx1 and higher vimentin expression were found to be prognostic factors for regional metastatic disease." (PMID 36833374, 2023). "There was also a stark difference when the matching pairs of primary and metastatic tumours were examined for VIM expression; the matching metastatic tumours had significantly higher expression of VIM than metastatic primary tumours." (PMID 37174052, 2023). "While E-Cadherin levels were variable with the highest expression in the normal mucosa, Vimentin was virtually undetectable in lung and liver metastatic tumors." (PMID 35837106, 2022). "Of note, IHC analysis showed lower expressions of cyclin D1, c-MYC, p-IKKα/β, p-p65, and vimentin but higher expression of E-cadherin in TUBB4A KO metastatic tumors compared to scrambled metastatic tumors." (PMID 35589707, 2022). "We performed IHC staining to evaluate the expression of E-cadherin, N-cadherin, and vimentin in the metastatic tumor tissues." (PMID 35942366, 2022). "All of the metastatic tumors were confirmed as carcinomas by vimentin and pan-cytokeratin (pan-CK) IHC staining." (PMID 34438836, 2021). "Immunohistochemistry of the primary and metastatic tumor demonstrated vimentin expression by neoplastic cells." (PMID 33602243, 2021). "Immunofluorescence was presented for evaluating the expression of ADAR1, CALR, E-cadherin, Vimentin, and β-catenin proteins in peritoneal metastatic tumor tissues." (PMID 35003354, 2021). "Conversely we observed genes associated with aggressive metastatic disease and EMT (VIM, SPARC, ZEB1, SNAI2, CTSB) upregulated in lung populations compared to lymph nodes." (PMID 34579762, 2021). "Vimentin, along with Zeb1, are widely regarded as markers of EMT and have been implicated in the development of metastatic disease in many cancers, including prostate." (PMID 32986721, 2020).
metastatic tumors (continued). "IHC of vimentin in this study also revealed that metastatic neoplasm numbers in the liver of LXRα knockdown groups were decreased compared to NC groups." (PMID 30770793, 2019). "Our finding that ajoene increases the expression of vimentin in cancer cells is therefore surprising and contradictory to the role that vimentin plays in progression of metastatic disease." (PMID 30894168, 2019). "The expression of E-cadherin and vimentin was also detected in metastatic tumor tissues located in the trachea and main bronchus from 12 cases with NSCLC by immunohistochemistry." (PMID 31969824, 2019). "Vimentin has been defined for both primary and metastatic tumours of patients with oesophageal squamous-cell carcinoma." (PMID 30248895, 2018). "The IHC assay of E-cadherin and Vimentin revealed that the protein expressions of peritoneal metastatic tumors were consistent with those in lung metastatic tumors." (PMID 30154451, 2018). "In HNSCC patients, significantly higher MMP-3, MMP-9 and vimentin levels were found in metastatic tumors." (PMID 28489600, 2017). "Nakajima and colleagues investigated the expression level of EMT markers such as N-cadherin, E-cadherin and vimentin in pancreatic primary and metastatic tumors." (PMID 27101285, 2016). "ISA-2011B-treatment also led to an inhibition in the expression of vimentin, a bio-marker for metastatic tumors, in the infiltrating tumor cells at the invasive front." (PMID 27588408, 2016). "The results showed a significant decrease in the Sufu expression of metastatic tissues compared with matched primary tumors (P < 0.0017), which are consistent with the E-cadherin and vimentin expression panels in primary and metastatic tumors." (PMID 26462018, 2015). "Both podoplanin and vimentin regulate processes of cell motility and invasion, and their expression often correlates with metastatic disease, and poor prognosis." (PMID 24598827, 2014). "A panel of immunohistochemical markers, including CD10, RCC, and vimentin, has been proposed for the identification of renal origin of a metastatic tumour." (PMID 23402579, 2013). "In 12 (48%) of 25 patients with metastatic disease, all the CTCs were double-positive (vimentin+ CK+) compared with only 6 (27%) of 22 patients with early disease who had exclusively vimentin+CK+ CTCs (P = 0.048)." (PMID 21663619, 2011). "Notably, SCORT‐CasRx‐pre‐gHoxB13 treatment significantly reduced the expression of extracellular vimentin and CD31, suggesting its inhibition of the angiogenesis associated with metastatic tumors." (PMID 40349174, 2025). "E-cadherin influences calcium-dependent cell-to-cell adhesion and inhibits the growth/metastasis of epithelial cancers, while Vimentin is a mesenchymal intermediate filament that helps coordinate various signaling pathways and has been shown to be elevated in metastatic tumors." (PMID 36558560, 2022). "In order to investigate whether the different anatomic location of orthotopic and metastatic PDX affected the expression of EMT-associated factors, we first compared the expression of E-Cadherin and Vimentin in primary, orthotopic and metastatic tumor tissues." (PMID 35837106, 2022). "Interestingly, tumor cells harboring KRAS G12V upregulate several genes associated with more aggressive or metastatic tumors, including COL1A1, VIM and MUC5B 42–44." (PMID 35995947, 2022). "Strong immunoreactivity to metastatic marker, Slug/Snail, mesenchymal markers, Vimentin and N-cadherin, epithelial marker, E-cadherin, and proliferative marker Ki67 was found in immunohistochemical observation of the metastatic tumor in liver compared to the primary tumor in spleen." (PMID 31450740, 2019). "Thus, they proposed that a block of the vimentin–integrin relationship represents a potential therapy for metastatic tumours." (PMID 30248895, 2018).
metastatic tumors (continued). "However, the CK+CTCs (CK+/Vimentin-/CD45-CTC plus CK+/Vimentin+/CD45-CTC) subset alone cannot distinguish metastatic from non-metastatic disease (15.24±12.72 vs 10.28±5.076cells/mL; P=0.3977)." (PMID 28039472, 2017). "A statistically significant correlation between the number of CTCs expressing Twist and vimentin in patients with both early stage and metastatic disease was demonstrated (P = 0.005 and P = 0.027, respectively), suggesting that both biomarkers were simultaneously expressed in CTCs." (PMID 21663619, 2011). "In this article, the high expression levels of CD10, vimentin (VI), and CAM5.2 further support the diagnosis of metastatic tumors." (PMID 40313249, 2025). "Overexpression of vimentin correlates with more metastatic disease, EMT induction, and poor prognosis; several studies support that WA treatment suppresses expression of vimentin and initiates its disassembly." (PMID 36701406, 2023). "The differential diagnosis between parathyroid and thyroid tumours, paraganglioma, haematological or metastatic tumours can be clarified via PTH, chromogranin A, TTF-1, calcitonin, LCA, CD56 and vimentin, among others." (PMID 35805976, 2022). "We also found that the E-cadherin expression was decreased, while vimentin expression was increased in human NSCLC tissues and metastatic tumor tissues located in the trachea and main bronchus." (PMID 31969824, 2019). "Among the patients with liposarcoma, synovial cell or spindle cell sarcoma, the CD45-/VIM+/TLE1+ phenotyping panel identified CTCs in 8/9 patients, ranging from 18 to 3,711 cells, consistent with the prior diagnosis of metastatic disease." (PMID 28403214, 2017). "When examining the total CTC count (CK+/Vimentin-/CD45-CTC plus CK+/Vimentin+/CD45-CTC plus CK-/Vimentin+/CD45-CTC), a significant difference was found between metastatic and non-metastatic disease (20.89±14.57 vs 8.428±5.858 / mL blood; P=0.0030)." (PMID 28039472, 2017). "In addition, we found that tumor cells expressed higher levels of BMP2, N-cadherin, Vimentin and p-SMAD1/5 in the shLacZ group than in the shBMP2 group by IHC both in primary tumors (right lung) and metastatic tumors (left lung)." (PMID 36175474, 2022). "Moreover, immunohistochemistry (IHC) staining of primary and metastatic tumors showed that PTK6 reversed the effects of PSPC1 on downregulating E-cadherin and upregulating vimentin, β-catenin, c-Myc and Wnt3a." (PMID 31844057, 2019). "This supports the hypothesis that targeting vimentin to inhibit EMT would have limited adverse effects on nonmalignant cells while effectively impeding cancer progression to metastatic disease." (PMID 37915048, 2023). "Thus, it is still debatable as to why vimentin expression in certain contexts correlates with invasion (e.g., metastatic disease) while in other systems re-expression does not." (PMID 24069380, 2013). "Conversely, the few metastatic tumors formed in the lungs with KPV−/− cells were sparse and small; as expected, these tumors did not express vimentin." (PMID 37161053, 2023). "Consistent with the previous results, lung metastatic tumor treated with Tan IIA had a higher expression of E-cadherin and lower expression of N-cadherin, Vimentin, and Snail compared with those from the tumor without Tan IIA treatment." (PMID 33192529, 2020). "The IHC assay of lung metastatic tumors revealed that knockdown of COL10A1 enhanced the expression of E-cadherin (epithelial marker) and decreased the expression of Vimentin (mesenchymal marker), while there was not significant decrease in SOX9 expression." (PMID 30154451, 2018).
lymph node metastasis (57 papers, 2007 to 2026). "Loss of E-cadherin and vimentin expression was associated with adverse clinicopathological features, including advanced stage, lymph node metastasis, and poor differentiation." (PMID 42278528, 2026). "It was recently discovered that the loss of vimentin in preoperative biopsies serves as an independent predictor of poor prognosis and lymph node metastases." (PMID 39851801, 2025). "Loss of vimentin expression in preoperative biopsies significantly associates with lymph node metastases within all endometrial cancer patients, as well as endometrioid tumors." (PMID 39516342, 2024). "Our analyses reveal that loss of vimentin expression in preoperative samples independently predicts lymph node metastasis in multivariate models." (PMID 39516342, 2024). "Loss of vimentin in preoperative biopsies serves as an independent predictor of poor prognosis and lymph node metastases." (PMID 39516342, 2024). "Markedly, patients with loss of vimentin were more often diagnosed with deep myometrial infiltration (≥50%, Chi-share, P < 0.001), lymph node metastases (Chi-square, P = 0.001), and disease recurrence (Chi-square, P < 0.001)." (PMID 39516342, 2024). "Most interestingly, when PD–L1 and vimentin were associated, the correlation with worse prognostic factors (dedifferentiation and lymph node metastases) was stronger." (PMID 31546725, 2019). "Our data showed that Vimentin expression is considerably associated with the onset age (P = 0.007), lymph node metastasis (P = 0.007), lymphatic invasion (P = 0.024), disease recurrence (P < 0.001), and the clinical prognosis of patients (P < 0.001)." (PMID 28912668, 2017). "And fourth, higher vimentin expression was associated with lymph node metastasis and poor prognosis in clinical OSCC sample analysis." (PMID 27966589, 2016). "Taken together, the IHC staining analysis showed that vimentin upregulation was strongly associated with lymph node metastasis in OSCC patients." (PMID 27966589, 2016). "E-cadherin and vimentin were strongly associated with the depth of tumor invasion, lymph node metastasis and advanced TNM stage." (PMID 27835885, 2016). "We have found that the level of co-expression of E-cad/vimentin was associated with lymph node metastasis (LNM) and poor pathological TNM stages and poor clinical survival." (PMID 26231404, 2015). "Next, we observed that Vimentin expression in ICC was linked originally to lymph node metastasis and associated with poor prognosis of ICC." (PMID 24816558, 2014). "We analyzed the relationship between EMT (assessed by staining for E-cadherin and Vimentin) and the expression of Brachyury in association with lymph node metastasis in oral SCC." (PMID 23076115, 2012). "Interestingly, vimentin loss independently predicted lymph node metastases, with an HR of 1.83 (95% CI 1.13–2.95, P = 0.014)." (PMID 39516342, 2024). "Additionally, it has been shown that tissue expressions of certain biomarkers, such as Cytokeratin, Podoplanin, Vimentin, Programmed Cell Death Ligand-1, or Epidermal Growth Factor Receptor, are significantly associated with the risk of lymph node metastasis." (PMID 37373623, 2023). "Vimentin is a cytoskeletal protein that is expressed in mesenchymal cells (fibroblasts, endothelial cells, lymphocytes) but not in healthy epithelial cells, and its upregulation in tumors is linked with lymph node metastasis." (PMID 35089096, 2022). "The current study demonstrated that high vimentin expression with loss of E-cadherin expression was correlated with lymph node metastasis, distant metastasis, disease progression and a poor prognosis in patients with grade 1 and 2 pNETs who underwent resection." (PMID 33789624, 2021). "However, higher Vimentin expression was associated with poor cell differentiation and lymph node metastasis." (PMID 28570699, 2017).
lymph node metastasis (continued). "However, the increased expression of vimentin in OSCC was significantly associated with lymph node metastasis, clinical stage, pathological grade, recurrence and overall survival." (PMID 26769084, 2016). "Additionally, we investigate whether assessing vimentin expression in preoperative samples could help improve the identification of patients with high-risk disease, including lymph node metastases, in a large international multicentre patient series." (PMID 39516342, 2024). "In colorectal carcinogenesis, vimentin is identified as a predictive marker for lymph node metastasis, higher tumor grade, poor prognosis, and decreased survival." (PMID 40468102, 2025). "Slug and Vimentin levels were significantly increased in patients with T-stage ≥ T3, while patients who had lymph node metastasis had significantly higher HAS-2, SNAI1, TWIST1, N-Cadh, Slug, and MMP-9." (PMID 40149256, 2025). "Our study is the first to report that vimentin is an independent predictor of poor prognosis and lymph node metastasis." (PMID 39516342, 2024). "Expression levels of vimentin were analyzed in conjunction with clinical characteristics for predicting disease-specific survival and lymph node metastases." (PMID 39516342, 2024). "In the lymph node metastasis, we found that entotic figures were visible within tissue sections presenting a high expression of E-cadherin and low vimentin expression." (PMID 37047791, 2023). "For each patient, the following characteristics were evaluated: overall survival; recurrence-free survival; lymph node metastasis; lymphovascular space invasion; and pathological findings, including immunohistochemical analysis of vimentin." (PMID 37717112, 2023). "Jin and colleagues have also identified vimentin as an independent prognosticator of lymph node metastasis in esophageal squamous cell carcinomas (ESCC)." (PMID 35207438, 2022). "While 74.2% of primary ESCC tumors showed elevated vimentin expression, the incidence of lymph node metastasis was reported in 71.9% of vimentin-positive tumors compared to 35.5% in vimentin-negative ESCC tumors." (PMID 35207438, 2022). "An increasing number of studies have described the role of vimentin in lymphatic invasion and lymph node metastasis of oral, esophageal, gastric, prostate, and colorectal squamous cell carcinomas." (PMID 35207438, 2022). "In CRC, high vimentin expression predicts poor disease-free survival and overall survival 38 and it is a biomarker for lymph node metastasis." (PMID 31737118, 2019). "MAP2K4 and Vimentin co-expression levels were positively correlated with the pathologic grade, tumor size, lymph node metastasis presence, and invasion (P<0.001)." (PMID 31761784, 2019). "Upregulation of SNAI2 significantly correlates with strong vimentin expression, and both SNAI2 and vimentin expression is associated with lymph node metastasis and poor prognosis." (PMID 31641356, 2019). "In univariate analysis, co-expression of PD–L1 and vimentin were influenced by age, tumor grade differentiation, and lymph node metastasis." (PMID 31546725, 2019). "When compared to Vimentin, a marker of mesenchymal-like cells metastasis, phage had more positive staining to the invasive front and lymph node metastasis." (PMID 30619759, 2018). "The results of the current meta-analysis also indicated that upregulated vimentin correlated well with lymph node metastasis, advanced TNM stages, and N stage." (PMID 29955607, 2018). "The expression levels of Bcl-2, Twist1, E-cadherin, N-cadherin, Vimentin and MMP-2/9 were significantly associated with lymph node metastasis, and the differences in the pathologic grades were significant." (PMID 28032603, 2017). "Thus, high vimentin expression might sever as a risk marker for lymph node metastasis in OSCC." (PMID 27966589, 2016).